C1QC (complement C1q C chain)
Diseases named in the same sentence as C1QC in open-access papers (continued):
Sharing a sentence is not in itself a finding about the gene and the disease.
Achalasia (1 paper, 2023). A disorder of esophageal motility characterized by the inability of the lower esophageal sphincter to relax during swallowing and by inadequate or lacking peristalsis in the lower half of the body of the esophagus. "C1QC+ macrophages also showed high upregulation of CALR in achalasia, a C1Q receptor gene that could contribute to microglial activation." (PMID 37542039, 2023). "We show C1QC+ macrophages and tissue-resident memory T cells (TRM), especially ZNF683+ CD8+ TRM and XCL1+ CD4+ TRM, are significantly expanded and localized surrounding the myenteric plexus in the LES tissue of achalasia." (PMID 37542039, 2023).
Alzheimer disease (1 paper, 2016). A progressive, neurodegenerative disease characterized by loss of function and death of nerve cells in several areas of the brain leading to loss of cognitive function such as memory and language. "Finally, we successfully verified significantly lower levels (p<0.05) of eight proteins (A2GL, APOM, C1QB, C1QC, C1S, FBLN3, PTPRZ, and SEZ6) in Alzheimer’s disease compared to controls using an antibody-based detection method." (PMID 26950848, 2016).
amyloid (1 paper, 2023). "These genes, Thy1, Gfap, Tyrobp, Ctsd, Cst7, C1qb, Lyz2, Ctss, Trem2, Mpeg1, Hexb, Cd68, C1qb, C1qa, Ctsz, Grn, Laptm5, B2m, C1qc, Hexa, and Serpina3n, were increased in the 7-month-old 5XFAD model in the cortex and associated with amyloid plaque image patterns." (PMID 38036733, 2023).
anemia (1 paper, 2024). A reduction in the number of red blood cells, the amount of hemoglobin, and/or the volume of packed red blood cells. "Our results indicated that LBZT exerts therapeutic effects against anemia by regulating the expression of complement C1QA, C1QC, C5, C8A and C8B and the subsequent complement and coagulation cascades." (PMID 39021933, 2024).
Apathy (1 paper, 2025). Apathy is a quantitative reduction of interest, motivation and the initiation and persistence of goal-directed behavior, where often the accompanying emotions, thoughts, and social interactions are also diminished. "Composite apathy scores were strongly and positively correlated with mRNA fold changes for all examined genes: Tyrobp, Trem2, C1qa, C1qb, C1qc, C3, C3ar1, and Cd33 (p < 0.0001)." (PMID 41377997, 2025).
asthma (1 paper, 2021). "KEGG pathway analysis results and GSVA results show that genes related to allograft rejection, asthma, and autoimmune thyroid disease pathways were enriched or upregulated in the LAPTM5, C1QC, SLCO2B1 and CSF1R high expression groups." (PMID 33428598, 2021).
cervical (1 paper, 2021). "In conclusion, C1QC+ and SPP1+ TAMs gene signatures derived from TAMs can divide cervical patients into subgroups with different prognosis and tumor stage, which may due to different immune cell infiltration." (PMID 34295336, 2021).
Cirrhosis (1 paper, 2023). A chronic disorder of the liver in which liver tissue becomes scarred and is partially replaced by regenerative nodules and fibrotic tissue resulting in loss of liver function. "Through Cell Phone analysis, we found that C1QC and SLC40A1 macrophages were also associated with liver fibrosis and cirrhosis, which might act by interacting with NK and MAIT cells." (PMID 36845083, 2023).
colitis (1 paper, 2023). Inflammation of the colon. "Whereas resident macrophage marker C1qb and C1qc were reduced in CD45+ cells from Il17b-/- colitis mice (P < 0.05)." (PMID 36814913, 2023).
colorectal cancer (1 paper, 2022). A primary or metastatic malignant neoplasm that affects the colon or rectum. "Despite the existence of multiple well-characterized colorectal-cancer-associated macrophage subgroups, including C1QC+ TAMs, SPP1+ TAMs, and FCN1+ TAMs, we identified a kind of tumor-resident FOLR2+ LYVE1+ macrophage subgroup in colorectal cancer." (PMID 36172359, 2022).
colorectal tumors (1 paper, 2019). "Specifically, cytokines that were previously shown to correlate with the cytolytic index (C1QA, C1QB, C1QC, CXCL9, CXCL10, CXCL11 and CXCL13), were upregulated in CYT-high colorectal tumors." (PMID 31429779, 2019).
congenital cataracts (1 paper, 2023). "We identified 18 HUB genes, among which four core genes, C1qa, C1qb, C1qc, and Cd74, were closely related to congenital cataracts induced by Crim1 mutation." (PMID 36586009, 2023). "In conclusion, through comprehensive biological analysis of the GSE62561 gene expression profile, a total of 750 DEGs were identified, of which C1qa, C1qb, C1qc, and Cd74 may be related to the occurrence and development of congenital cataracts caused by Crim1 mutations." (PMID 36586009, 2023). "In addition, some researchers have found that the pathogenesis of congenital cataracts caused by TDRD7 deficiency may be related to the immune response, defence response, and related genes LY86, C1QA, C1QB, and C1QC." (PMID 36586009, 2023). "In this study, the C1qa, C1qb, and C1qc genes were upregulated in mutant mice, suggesting that the early development of congenital cataracts may activate the classical complement system, leading to synaptic disorders and neurodegenerative diseases, thus promoting the development of CC." (PMID 36586009, 2023).
cryptococcal infection (1 paper, 2022). "In particular, of the top 10 genes with the largest change in response to cryptococcal infection, three are components of the classical complement activation pathway: C1qb, C1qa, and C1qc." (PMID 35628686, 2022).
diffuse large B-cell lymphoma (1 paper, 2022). "Upregulation of C1QA, C1QB, and C1QC in peripheral T-cell lymphoma and upregulation of C1QC in Epstein-Barr Virus-positive diffuse large B-cell lymphoma have been reported previously." (PMID 36873459, 2022).
esophageal squamous cell carcinoma (1 paper, 2023). Esophageal squamous cell carcinoma (ESCC) is a type of esophageal carcinoma (EC) that can affect any part of the esophagus, but is usually located in the upper or middle third. "We analyzed two single-cell RNA sequencing (scRNA-seq) datasets (GSE145370 and GSE160269) of esophageal squamous cell carcinoma to identify a novel TREM2-positive TAM subpopulation characterized by upregulation of TREM2, C1QC, C1QB, C1QA, SPP1, and APOE." (PMID 37187751, 2023).
glaucoma (1 paper, 2019). Increased pressure in the eyeball due to obstruction of the outflow of aqueous humor. "In the current datasets, optic nerve head monocyte-like cells highly express various complement genes (including C1qa, C1qb, C1qc, C3, and C3ar1), and complement activation is implicated in human glaucoma." (PMID 30670050, 2019).
infarcts (1 paper, 2025). "Notably, LTBP1 and CRIP1, along with C1QC and PRSS23 (linked to WMH and infarcts) and CEMIP and ELN (associated with WMH and microbleeds), showed strong co-localization with ThioS- positive vascular amyloid deposits, but not with parenchymal plaques." (PMID 41282800, 2025).
keloid (1 paper, 2022). An irregularly shaped, elevated mark on the skin caused by deposits of excessive amounts of collagen during wound healing. "Since the downstream genes of RB1 are related with M2 macrophages, for example: C1QC,C1QB,MRC1, fibroblasts in keloid may be beneficial for the transition and proliferation of M2 macrophages." (PMID 35990663, 2022).
lung carcinoma (1 paper, 2023). "In contrast, C1QC+ TAMs expressed the classical TAM-associated genes C1QA, C1QB, C1QC, APOE, and TREM2, which were previously reported in lung cancer." (PMID 37383234, 2023).
lung squamous cell carcinoma (1 paper, 2023). "Existing research has suggested that high mRNA expression of C1QC and CSF1R is associated with immunosuppression in the lung squamous cell carcinoma tissue microenvironment and worsen patient survival outcomes." (PMID 36992705, 2023).
memory impairment (1 paper, 2022). "As a result, 3 DEmRNAs from CCI with memory impairment model rats (ATF3, C1QC, and CD68) and 13 DEmRNAs from SNI and CCI models (ADAMTS2, BCL6B, CLCF1, RBP1, and TPBG, among others) overlapped with SNI and CCI models, respectively." (PMID 35547819, 2022).
Myocardial fibrosis (1 paper, 2021). "It is believed that the components of the C1qc complement are responsible for “aging,” myocardial fibrosis." (PMID 34867466, 2021).
myocardial infarct (1 paper, 2024). "These include C1qa, C1qb, and C1qc, all components of the membrane attack complex, as well as C5ar1, the receptor for the complement anaphylatoxin 5a, which can stimulate immune cells in myocardial infarct models." (PMID 39202335, 2024).
Pleural effusion (1 paper, 2014). The presence of an excessive amount of fluid in the pleural cavity. "We also show here that TB pleurisy was associated with a higher level of C1qC in pleural effusion than was seen in non-TB pleurisy." (PMID 24647646, 2014). "Interestingly, we found that the C1qC level in pleural effusion of TB patients is significantly higher than in non-TB patients (non-inflammatory diseases)." (PMID 24647646, 2014).
pulmonary fibrosis (1 paper, 2022). Chronic progressive interstitial lung disorder characterized by the replacement of the lung tissue by connective tissue, leading to progressive dyspnea, respiratory failure, or right heart failure. "C1qa, Fcgr1, C1qb, C1qc, Ccr5, Slc11a1, Aif1, Emr1 and Cxcl10 were identified as the most closely connected module which were highlighted in yellow, including 9 nodes and 32 edges, and the genes in this region were upregulated in pulmonary fibrosis." (PMID 35078421, 2022).
renal fibrosis (1 paper, 2023). A final common manifestation of a wide variety of chronic kidney diseases characterized by glomerulosclerosis and tubulointerstitial fibrosis. "Moreover, the observed alterations in the mRNA expression of C1QA and C1QC genes could also be a secondary treatment effect, means secondary to primary effects of empagliflozin on for example renal fibrosis." (PMID 36779666, 2023).
retinal degeneration (1 paper, 2008). Degeneration of the retina. "Complement component 1, q subcomponent, alpha and c polypeptides (C1qα and C1qc), which are upregulated in retinal degeneration, are also localized to the LCA9 and RP32 loci." (PMID 18776951, 2008).
steatosis (1 paper, 2022). Increased lipid within the cytoplasm of cells. "The expression of C1qa, C1qb, C1qc, and C2 in KCs was significantly higher in patients with severe steatosis when compared to healthy controls." (PMID 36304458, 2022). "KCs in healthy and steatosis patients highly expressed C1qa, C1qb, C1qc, and ApoE transcripts." (PMID 36304458, 2022).
tumor (78 papers, 2014 to 2026). "Previous studies have linked C1qc+ TAMs to phagocytosis, antigen presentation, and anti-tumor immune response, while Spp1+ TAMs are often associated with immunosuppression." (PMID 40917508, 2025). "In depth analysis of the different cell types identified within the myeloid lineage revealed that AKR1B1 expression was the highest in tumor associated macrophages (TAMs) that express C1QC (complement protein C1Q) gene." (PMID 40396420, 2025). "C1QC + macrophages are tumor-associated macrophages with complement activation, antigen processing and presentation." (PMID 37344903, 2023). "While cluster 2 highly expressed C1qa/C1qc genes that were found upregulated in a previously reported M2-like tumor associated macrophage cluster." (PMID 35260564, 2022). "C1QC+ tumor-associated macrophages and INHBA+ monocytes showed a significant reduction in inflammation-related pathways, including the interferon alpha pathway, IL-6 pathway, and interferon gamma pathway." (PMID 36052088, 2022). "Among macrophages, most cells expressed high levels of complement (C1qa, C1qb, C1qc), which in tumor-associated macrophages have been reported to correlate with immune exhaustion and poor survival." (PMID 36433954, 2022). "Cells in Mac_0 were characterized by expression of complement-related genes (C1qa, C1qb, C1qc) and cytokines (Spp1, Ccl12), while cells in Mac_1 expressed higher levels of several tumor-associated macrophage-related genes such as Arg1, Cebpb, and Ier3." (PMID 34030676, 2021). "Furthermore, we identified several tumour-associated macrophages, including C1QC+ macrophages, ISG-15+ macrophages, NLRP3+ macrophages and CCL20+ macrophages." (PMID 37735150, 2023). "Additionally, M2-related macrophages, including INHBA+ monocytes and C1QC+ tumor-associated macrophages, were significantly increased in ASPCs, followed by a reduction in juvenile macrophages in the tumor microenvironment (FCN+ monocytes)." (PMID 36052088, 2022). "Prior work has shown how sub-units of the C1Q complex, including C1QA, C1QB, and C1QC, are associated with modulating the local environment of tumor cells and may therefore reflect local microenvironment remodeling after brain injury." (PMID 36670596, 2022). "Interestingly, FOLR2, CD163, LILRB5, CD209 and C1QC were identified as genes of the “anti-inflammatory gene set”, whose expression is also seen in tissue-resident macrophages and tumor-associated macrophages." (PMID 32532019, 2020). "Complement components C1qA, C1qB, and C1qC were significantly increased in tumor-bearing mice that had been irradiated, whereas similarly aged mice without tumors displayed a decline in complement system activity." (PMID 40757647, 2025). "Most myeloid components were mainly present in the primary tumor tissue, of which the number of C1QC+TAMs was the highest in the primary tumor among all myeloid cells, followed by S100A8+monocytes, whereas these cells were scarce in the adjacent normal tissue." (PMID 39323622, 2024). "Recent evidence suggested that C1qA, C1qB, C1qC positively influence anti-tumor through antibody-mediated immune responses." (PMID 39232806, 2024). "Classical antibody-mediated complement activation, the complement cascade and C1q complex pathways implicate the anti-tumor role of C1QC+ TAMs." (PMID 39232806, 2024). "C1QC+ TAMs expressing classical complement molecules C1q genes exert anti-tumor effects through antigen presentation, phagocytosis and enhancing antibody-mediated tumor immunity." (PMID 39232806, 2024). "Complement C1q C chain (C1QC) is a polypeptide in serum complement system and is involved in tumorigenesis and the modulation of tumor microenvironment (TME)." (PMID 36992705, 2023). "Rather, C1QC+ TAMs showed enrichment of tumor vasculature, tumor angiogenesis, and ECM regulator pathways, while complement activation and cytokine pathways were significantly enriched in VCAN+ TAMs." (PMID 37383234, 2023).
tumor (continued). "SPP1+ TAMs are enriched for pathways involved in tumor angiogenesis, tumor vasculature and colorectal adenoma, while C1QC+ TAMs are enriched for complement activation and antigen processing and presentation pathways." (PMID 36189323, 2022). "In the endometrial macrophages, the most significantly expressed genes were C1qa and C1qc, components of the C1q complex of the complement system which can also act as a tumor-promoting factor." (PMID 36424602, 2022). "Among them, Module2 (highly express RNASE1, C1QA, CD163, CD14, C1QC, FCGRT, and MS4A7) and Module10 (highly express APOC1, CTSB, CTSL, and TYROBP) are more likely to display the characteristics of tumor-associated macrophages (TAMs)." (PMID 35990663, 2022). "C1QC, as important gene for the complement system and thus innate immune response, has been found to be a part of tumor microenvironment of different cancer entities." (PMID 35634436, 2022). "In the tumor tissue, TAMs and cDCs became the core of communications, and C1QC+ TAMs and two groups of cDCs interacted with T cell subsets, implicating the regulation of antitumor T cell function." (PMID 35504878, 2022). "The majority of these are tumor-derived, although several host proteins (C1qa, C1qc and Vwf) are also identified as being downstream of TGFβ." (PMID 24618895, 2014). "Hence, the TME in CRC is composed of specialized TAM subpopulations with opposing roles: immune coordination (C1QC+) with anti-tumor functions versus stromal activation (SPP1+) involved in tumor progression signaling." (PMID 41450739, 2025). "In addition, enhanced expression of proteins related to antigen processing and immune activation, including HLA-DRA, ITGAM, and C1QC, reflected a strong inflammatory phenotype within the tumor tissue." (PMID 41480141, 2025). "Bulk analysis of PNF macrophages revealed a mixed M1 (anti-tumor)/M2 (pro-tumorigenic) RNA signature, and single cell analysis revealed a subpopulation marked by CC1qa, C1qb, and C1qc, previously identified in tumor-promoting macrophages correlating with T-cell exhaustion." (PMID 38458648, 2024). "Notably, VCAN+ TAMs were reprogrammed into C1QC+ TAMs with upregulated coinhibitor and downregulated coactivator expression in the tumor region, suggesting key roles of C1QC+ TAMs in the tumorigenesis of HCC." (PMID 37383234, 2023). "However, in tumor tissues, C1QC + macrophages receive CSF signaling from both MFAP5 + and FABP5 + fibroblasts, suggesting an immunomodulatory role in CRC." (PMID 37344903, 2023). "We observed that MFAP5 + fibroblasts were the main senders that could release complement C3 to interact with the receptors ITGAM/ITGB2, ITGAX/ITGB2, and C3AR1 of C1QC + macrophages in tumor tissues, thus activating the complement system." (PMID 37344903, 2023). "We observed that tumor-associated macrophages highly expressing C1QC, C1QA, and C1QB could be identified as C1QC + macrophages." (PMID 37344903, 2023). "We found that the mRNA expression of C1QA, C1QB, C1QC, C5AR1, C3AR1, C1QR (CD93), CR1, CR2, CR3 (ITGAM), and CR4 (ITGAX) were positively associated with almost all kinds of tumor immune cells, including CD8+ T cells, CD4+ T cells, B cells, macrophages, monocytes and DCs." (PMID 34813686, 2022). "Similarly, analysis of macrophages from the 3 states revealed that there were distinct genes in the Tumor macrophages which includes genes like Cotl1, Tgfbi, Fos, and Fn1 along with complement activation genes C1qa, C1qb, and C1qc." (PMID 35851387, 2022). "Based on these results, we can speculate that C1QA, C1QB, and C1QC play key roles in immune cell infiltration in the tumour microenvironment of SKCM." (PMID 36110204, 2022). "Finally, during survival in the tumor microenvironment, macrophages tended to differentiate into two subtypes of M2 macrophages, INHBA+ monocytes and C1QC+ tumor-associated macrophages." (PMID 36052088, 2022). "The mRNA expression of C1QC, CSF1R, LAPTM5 and SLCO2B1 was negatively associated with tumor purity." (PMID 33428598, 2021).